MDM2 (MDM2 proto-oncogene)
Diseases named in the same sentence as MDM2 in open-access papers (continued):
Sharing a sentence is not in itself a finding about the gene and the disease.
tumor (continued). "The expression of FRS2 was also compared with that of classic immunomarkers (MDM2 and CDK4) of this tumor entity." (PMID 34696768, 2021). "Due to the involvement in MDM2 inhibition resistance and because MDMX is itself involved in cancer development, MDMX became a target of anti-tumour treatment and several MDMX or dual MDM2-MDMX inhibitors were developed (summarised in Types of MDM2 inhibitors)." (PMID 34911439, 2021). "In tumor cells, activation of the PI3K/AKT signaling pathway leads to MDM2 phosphorylation at Ser166/186, which promotes the nuclear translocation of MDM2 and enhances its ubiquitination activity." (PMID 34298892, 2021). "miR-641 has been reported to be a tumor-suppressive miRNA by targeting various downstream genes, including ZEB1, HOXA9, MDM2, and YAP1." (PMID 34603448, 2021). "HDAC2 is co-expressed with MDM2, and HDAC2 inhibition results in decreased MDM2 expression and enhanced tumor cell apoptosis." (PMID 35008848, 2021). "The co-amplification of HMGA2, TSPAN31, and YEATS4 with MDM2 is frequently observed in DDLPS and is involved in tumor development." (PMID 34834427, 2021). "LPH-mediated co-delivery of miR-34a, and a combination of three small interfering RNAs (siRNAs) targeting c-Myc, MDM2 and VEGF inhibited tumor growth and had a synergistic effect when compared to delivering the therapeutics individually." (PMID 32102476, 2020).
tumor (continued). "The comparison of the status of HER2, MDM2, and c-MYC genes of the 37 GC patients’ CTC samples with that of the patients’ matched tumor tissues demonstrated that the mean interval between the CTC and tissue samples was equal to 20.1 days." (PMID 31454863, 2020). "Targeting of MDM2 was achieved by siRNA transfection or a selective MDM2 inhibitor, AMG-232 and tumor cells were tested in the T-cell co-culture system." (PMID 32655895, 2020). "For example, exosomes released from bone marrow mesenchymal stem cells can be internalized in tumor cells and elicit angiogenesis through transferring VEGF, CXCR4, α-SMA, and MDM2 mRNA transcripts." (PMID 32499786, 2020). "In the same tumour sets, the expression levels of target molecules (KLF5, TFDP1 and MDM2) decreased at the mRNA and protein levels." (PMID 32066912, 2020). "Histopathological findings revealed adipose tissue with lipoblasts and spindle cells and immunohistochemical staining (IHC) revealed the tumor cells were strongly positive for CDK4 and MDM2." (PMID 32438529, 2020). "The transplanted tumor volumes in the co-treatment group of MCF-7/DOX models were significantly lower than those in the NS (P<0.001), DOX (P=0.004) and MDM2/MDMX inhibitor groups (P=0.011) since day 3 until mice executed." (PMID 31892970, 2020). "E3 ligase MDM2, PARKIN and HUWE1 can catalyze ubiquitination of HIF-1α and targets it for degradation, thus exerting an anti-tumor effect." (PMID 33004065, 2020). "In a similar path, the same group described later a series of pyrrolones 199 which showed to be striking activity as MDM2/MDMX dual inhibitors, impeding the tumor growth in the A549 xenograft model." (PMID 32326087, 2020).
tumor (continued). "In result, the increased expression of VEGF secondary to MDM2 amplification can putatively lead to aberrant ICB responses through changes in expression levels of both PD-1 and PD-L1 and changes in tumour-intrinsic signalling." (PMID 32230745, 2020). "Each tumor was assigned a BCL11A and MDM2 expression score based on the staining intensity and staining extent." (PMID 32266150, 2020). "Knocking down MDMX or MDM2 in MDA-MB-231 cells reduced cell migration and CTC detection, but only MDMX knockdown reduced tumor volumes at early time points." (PMID 30642351, 2019). "In agreement with promoting tumor cell vitality, PDLIM7 was shown to stabilizes MDM2 by interfering with its autoubiquitination resulting in reduced responsiveness toward CDK4/6-inhibition by PD03329921 in cancer cells." (PMID 30371874, 2019). "To this end, we established PDCs from patient tumor tissues and characterized them via FISH using the MDM2 probe and karyotyping." (PMID 31126284, 2019). "Murine double minute 2 (MDM2) is one of 3 highly amplified genes (MDM1, MDM2 and MDM3) initially found in the Balb/c3T3 fibroblast cell line (3T3DM) of tumor-bearing mice." (PMID 31440117, 2019). "We validated the downregulation of PTGS2 and CXCR4 with MDM2 and MDMX knockdown in the tumors by performing qRT-PCR from the sets of primary tumor samples." (PMID 30642351, 2019). "Currently clinical trials are ongoing with the dual Mdm2/Mdm4 stapled peptide (ALRN-6924), which has been reported to be tolerated well in patients as well as demonstrating anti-tumour activity." (PMID 31784573, 2019). "We also observed decreased levels of G2/M proteins MDM2 and CDC2 in tumor specimens from mice treated with osthole." (PMID 30577812, 2018).
tumor (continued). "On the other hand, combination of MDM-2, c-myc and VEGF siRNAs also reduced tumor load in lungs (20–30%) and extended survival rate were found in comparison to control group." (PMID 29861465, 2018). "Therefore, we further emphasized our speculation that the concomitant up-regulation of MMP9 and THBS1 found in the LNCaP-MST cells may be due to MDM2 overexpression that can easily lead to the acquisition of aggressive tumor phenotype with increased metastatic potential." (PMID 29748481, 2018). "The targeted genotyping panels (T200/T200.1 and FM) detected several other CNAs, in addition to MDM2 and CDK4, and many of them were found in more than one tumor sample." (PMID 29731991, 2018). "We validated the focal status of gene amplification (size < 10Mb) for 2 tumours (focal amplification of CCND1 for tumour T8 and focal amplifications of DDR2, AKT2 and MDM2 for tumour T16) using array comparative genomic hybridization." (PMID 29416628, 2018). "Since USP15 also stabilizes MDM2 in cancer cells, in which MDM2 serves as a major survival factor, ablation of USP15 appears to inhibit tumor growth by both promoting anti-tumor T cell responses and causing tumor cell apoptosis." (PMID 30054854, 2018). "Blocking USP7 facilitates the E3 ligase MdM2 degradation, and by doing so the USP7 inhibitor controls the tumor growth significantly." (PMID 30344943, 2018). "Mouse double minute 2 (MDM2) and vascular endothelial growth factor (VEGF) are important molecules involved in tumor progression." (PMID 28274247, 2017). "We showed that tumor cells were positive for all of these biomarkers, and that there was also moderate to strong expression of OPN, MAPK, MDM2, PEDF and CD44 in the stroma cells." (PMID 29029440, 2017). "Meanwhile, concomitant overexpression of MDM2 and OV6 predicted rapid tumor relapse and a poor prognosis for HBV-related HCC patients." (PMID 28102846, 2017). "We tested the anti-tumor activity of 3C23K in in vitro assays with COV434-AMHRII used as tumor cells and monocyte-derived type 2 macrophages (MDM2) used as effector cells." (PMID 29245952, 2017). "Among the 10 amplification-based oncogenes, we identified that six genes (MDM2, MYC, MYCL, MYCN, NKX2-1, and SKP2) were amplified and overexpressed in ≥10 tumor samples." (PMID 28377632, 2017).
tumor (continued). "Our study suggests that the p14ARF rs3814960 and MDM2 rs34886328 SNPs can be used as predictive biomarkers of ESCC after radical resection in genotyping assays, in addition to the tumor stage." (PMID 27414035, 2016). "Downregulation of MDM2 by the developed polyplexes induced significant apoptosis of NSCLC PC9 cells in vitro, and inhibited the tumor growth in a PC9 xenograft tumor model." (PMID 27259273, 2016). "The primary tumor, the bland adipose tissue resected from the inguinal canal at the time of surgery, and the recurrent tumor all underwent FISH testing, which demonstrated MDM2 amplification in all three specimens." (PMID 26987706, 2016). "Of 64 spindle cell/pleomorphic neoplasms (in which DDL was a differential diagnosis), 21.9% showed MDM2 amplification." (PMID 25810689, 2015).